HELZ (helicase with zinc finger)
Description:
ATP-dependent RNA helicase that promotes degradation of mRNAs via its association with the CCR4-NOT deadenylase complex, leading to deadenylation, decapping, and subsequent degradation of target mRNAs. Can repress translation independently of mRNA decay in a manner dependent on both the CCR4-NOT complex and the helicase DDX6. Involved in promoting cell proliferation, translation initiation, and ribosomal protein S6 (RPS6) phosphorylation.
Synonyms: DRHC; KIAA0054; HUMORF5; DHRC
Tractability: Antibody: the Human Protein Atlas places it where antibodies can reach. PROTAC: ubiquitination databases record sites on it; its protein half-life has been measured.
Target class: Enzyme; Hydrolase
Gene: Protein-coding gene on chromosome 17 (67,070,444 to 67,245,989, reverse strand). Ensembl gene ENSG00000198265.
Subcellular location: Nucleus; Cytoplasm
Subcellular location (Human Protein Atlas): Nucleoli; Nucleoli rim; Actin filaments; Plasma membrane
Gene Ontology:
Molecular function: CCR4-NOT complex binding; protein binding; RNA binding; ATP binding; ATP hydrolysis activity; helicase activity; metal ion binding; RNA helicase activity
Biological process: negative regulation of translation; positive regulation of cell population proliferation; positive regulation of nuclear-transcribed mRNA catabolic process, deadenylation-dependent decay
Cellular component: cytoplasm; membrane; cytosol; P granule; nucleus
Genetic constraint (gnomAD): Loss-of-function variants: 18 observed, 166.64 expected, observed/expected ratio (o/e) 0.11, 90% interval 0.074 to 0.16. The upper end of that interval is the gene's LOEUF score, 0.16, which puts it in group 1 of 6, group 1 being the genes least tolerant of losing a copy. Missense variants: 1,523 observed, 2,068.4 expected, observed/expected ratio (o/e) 0.74, 90% interval 0.7 to 0.77. Synonymous variants: 710 observed, 742.66 expected, observed/expected ratio (o/e) 0.96, 90% interval 0.9 to 1.02.
Homologues: Orthologues: chimpanzee HELZ (99% identical), macaque HELZ (99% identical), dog HELZ (96% identical), pig HELZ (96% identical), rat Helz (92% identical), mouse Helz (92% identical), rabbit HELZ (90% identical), guinea pig HELZ (90% identical), tropical clawed frog helz (76% identical), zebrafish helz (61% identical), Drosophila melanogaster Helz (36% identical), Caenorhabditis elegans Y106G6D.5 (6% identical), and 2 more. Paralogues in human: MOV10L1 (12% identical), HELZ2 (11% identical), SETX (11% identical), ZNFX1 (10% identical), MOV10 (10% identical), IGHMBP2 (10% identical), AQR (9% identical), UPF1 (8% identical), DNA2 (8% identical), CT55 (1% identical).
Diseases named in the same sentence as HELZ in open-access papers:
HELZ is named in the same sentence as 5 diseases in open-access papers, as found by Europe PMC text mining. Sharing a sentence is not in itself a finding about the gene and the disease. The quoted sentences say what the papers report.
hepatoma (2 papers, 2011 to 2021). "However, this was based on semi-quantitative RT-PCR analysis of HELZ expression in 95 tumor cell lines and the observation that exogenous HELZ expression inhibited proliferation and colony formation of hepatoma cells in vitro." (PMID 21765940, 2011).
Hodgkins lymphoma (1 paper, 2011). A heterogeneous group of malignant lymphoid neoplasms of B-cell origin characterized histologically by the presence of Hodgkin and Reed-Sternberg (HRS) cells in the vast majority of cases. "The cell line L428 is also derived from an Hodgkin's lymphoma, but wild-type for HELZ, and served as positive control." (PMID 21765940, 2011). "Anti-HELZ antibody specificity was verified by RNA interference-mediated HELZ knock-down in HEK293 cells (stable clone 4–10) as well as by using the Hodgkin's lymphoma-derived cell line DEV that contains a 3-megabase homozygous deletion at 17q24.1–24.2, which includes, amongst others, HELZ." (PMID 21765940, 2011).
cancer (1 paper, 2011). A tumor composed of atypical neoplastic, often pleomorphic cells that invade other tissues. "Human HELZ has alternatively been termed down-regulated in human cancers (DRHC)." (PMID 21765940, 2011).
neurodegenerative disease (1 paper, 2018). A disorder of the central nervous system characterized by gradual and progressive loss of neural tissue and neurologic function. "Therefore, HELZ may have associations with the pathogenesis of neurodegenerative disease including AD25." (PMID 30478411, 2018).
HELZ also shares sentences with these, for which no sentence is quoted: tumor (2 papers).